SPIN4 (spindlin family member 4)
Description:
Binds to acetylated and methylated histones, including H3K4me3 and H4K20me3, probably acting as a histone reader that recognizes chromatin marks and mediates downstream cellular effects. Promotes canonical WNT signaling, and is involved in the down-regulation of cell proliferation.
Synonyms: FLJ44984; TDRD28; LJBS
Tractability: Small molecule: a high-quality ligand is known. PROTAC: ubiquitination databases record sites on it; a small molecule that binds it is known.
Target class: Reader; Epigenetic regulator
Chemical probes: VinSpinIn (high quality)
Gene: Protein-coding gene on chromosome X (63,347,228 to 63,351,332, reverse strand). Ensembl gene ENSG00000186767.
Subcellular location: Cytoplasm; Nucleus
Subcellular location (Human Protein Atlas): Cytosol; Nucleoplasm; Centrosome
Gene Ontology:
Molecular function: histone H3K4me3 reader activity; protein binding
Biological process: negative regulation of cell population proliferation; positive regulation of canonical Wnt signaling pathway; regulation of DNA-templated transcription; chromatin organization; gamete generation
Cellular component: chromatin; cytoplasm; nucleus; nucleoplasm
Homologues: Orthologues: chimpanzee SPIN4 (100% identical), macaque SPIN4 (99% identical), rabbit SPIN4 (99% identical), guinea pig SPIN4 (96% identical), pig SPIN4 (96% identical), rat Spin4 (96% identical), mouse Spin4 (96% identical), tropical clawed frog spin1 (72% identical), zebrafish spina (68% identical), zebrafish spinb (53% identical). Paralogues in human: SPIN1 (75% identical), SPIN3 (69% identical), SPIN2B (66% identical), SPIN2A (65% identical).
Diseases named in the same sentence as SPIN4 in open-access papers:
SPIN4 is named in the same sentence as 17 diseases in open-access papers, as found by Europe PMC text mining. Sharing a sentence is not in itself a finding about the gene and the disease. The quoted sentences say what the papers report.
overgrowth syndrome (2 papers, 2023 to 2024). A group of syndromes caused by genetic birth defects that may lead to the development of malignancies. "In humans, SPIN4 is associated with overgrowth syndrome and hyperekplexia." (PMID 39682483, 2024). "Taken together, our findings provide strong evidence that SPIN4 is an epigenetic reader that negatively regulates mammalian body growth and that loss of SPIN4 causes an overgrowth syndrome in humans, expanding our knowledge of the epigenetic regulation of human growth." (PMID 36927955, 2023).
autism (1 paper, 2025). Persistent deficits in social interaction and communication and interaction as well as a markedly restricted repertoire of activity and interest as well as repetitive patterns of behavior. "Several of these functionally uncharacterized proteins are associated with human diseases including ciliary dyskinesia (CLXN), Lui-Jee-Baron syndrome (SPIN4), lymphoblastic leukemia (LNP1, SLX4IP), lethal skeletal dysplasia (TMEM263), and association to autism and fragile X syndrome (DIPK2B)." (PMID 40425816, 2025).
Cognitive impairment (1 paper, 2023). Abnormal cognition is characterized by deficits in thinking, reasoning, or remembering. "However, the proband lacking functional SPIN4 in our study did not have developmental delay or cognitive impairment." (PMID 36927955, 2023).
glioblastoma (1 paper, 2021). The most malignant astrocytic tumor (WHO grade IV). "Since copy number alteration may affect tumor development through changes in gene expression, the amplification of chromosomes Xq11.1–Xq11.2 has been linked to high SPIN4 levels in glioblastoma." (PMID 34575061, 2021). "Additionally, in glioblastoma, the amplification of chromosomes Xq11.1–Xq11.2 has been linked to high SPIN4 levels, which may activate the Wnt signaling pathway." (PMID 34575061, 2021).
periodontitis (1 paper, 2018). An acute or chronic inflammatory process that affects the tissues that surround and support the teeth. "On the other hand, gain of genetic material on region Xq11.1 involved genes SPIN4 and LOC92249; losses and mutations on these genes have been associated with periodontitis phenotype." (PMID 30442194, 2018).
cancer (4 papers, 2020 to 2026). A tumor composed of atypical neoplastic, often pleomorphic cells that invade other tissues. "Using bioinformatics analysis, we further found that the tight junction proteins TJP1 and TJP2 show significant positive correlations with SPIN4 and are linked to cancer cell survival." (PMID 34575061, 2021). "In the current study, we investigated the prevalence of malignancies, along with body weight, body length, body composition and bone mineral density, in Spin4 knockout mice at 18 months of age." (PMID 41676612, 2026). "Collectively, SPIN4 may promote cancer cell survival in an EBV-independent manner and correlate with poor patient survival, further reflecting the intricate regulation of NPC." (PMID 34575061, 2021). "Using bioinformatics analysis, we further found that high SPIN4 level may link tight junctions to cancer cell survival." (PMID 34575061, 2021). "Nevertheless, the role of SPIN4 in cancer still lacks investigation." (PMID 34575061, 2021). "However, the SPIN4 and C10orf71 have not been reported associated with the development and progression of cancer." (PMID 31701684, 2020). "We found that the expression of SPIN4, EZH2, and DNMT3A to be elevated in many human cancers compared to the corresponding non-malignant tissue samples." (PMID 41676612, 2026).
neoplasia (2 papers, 2021 to 2026). "High SPIN4 expression in tumor samples was an unfavorable prognostic factor for all three endpoints at the univariate level: disease-specific survival (DSS), distal metastasis-free survival (DMeFS), and local recurrence-free survival (LRFS) (all p < 0.05)." (PMID 34575061, 2021). "Taken together, our current findings confirm that loss of SPIN4 causes overgrowth in mice (in terms of body length) and is associated with increased prevalence in neoplasia; but does not appear to affect adiposity or bone density." (PMID 41676612, 2026). "In addition, high SPIN4 expression in tumor specimens was also unfavorably prognostic of all three endpoints (all p < 0.05) analyzed." (PMID 34575061, 2021). "We collected 124 tumor samples from NPC patients receiving biopsy, and the expression level of SPIN4 was evaluated by immunohistochemistry." (PMID 34575061, 2021).
infection (1 paper, 2020). The state of being infected such as from the introduction of a foreign agent such as serum, vaccine, antigenic substance or organism. "Unexpectedly, however, spin-1(ok2087) (p < 0.0001) and spin-4(ok2620) (p = 0.0062) mutant worms were more resistant to P. aeruginosa PA14 infection than the wild-type worms." (PMID 33105563, 2020). "We also found that sphk-1 (p = 0.0086), spin-2 (p < 0.0001), and spin-3 (p < 0.0001) mutant worms were significantly more susceptible to infection by E. faecalis strain MMH594, whereas spin-4 (p = 0.0222) mutant worms were modestly more resistance than N2." (PMID 33105563, 2020).
SPIN4 also shares sentences with these, for which no sentence is quoted: ciliary dyskinesia (1 paper); developmental delay (1); fragile X syndrome (1); hyperekplexia (1); Lethal skeletal dysplasia (1); Lui-Jee-Baron syndrome (1); lymphoblastic leukemia (1); nasopharyngeal carcinoma (1); renal carcinoma (1).